HIF1A (hypoxia inducible factor 1 subunit alpha)
Diseases named in the same sentence as HIF1A in open-access papers (continued):
Sharing a sentence is not in itself a finding about the gene and the disease.
breast tumor (continued). "In addition, we have found that factor 26 (1q CNA) is negatively correlated with HIF-1α protein and hypoxia pathways in breast tumors and cell lines." (PMID 20824128, 2010). "For example, aberrant STAT3 signaling promotes breast tumor progression through deregulation of the expression of downstream target genes, which control proliferation (Bcl-2, Bcl-xL, survivin, cyclin D1, c-Myc, and Mcl-1), angiogenesis (Hif1α and VEGF), and EMT (vimentin, Twist, MMP-9, and MMP-7)." (PMID 36446524, 2023). "Furthermore, it is unclear whether the increase in HIF-1α mRNA contributes to the increase in HIF-1α protein in BM-MSCs faced with breast tumors." (PMID 36230633, 2022). "Furthermore, as in the analysis of our mouse model, GSEA of these human tumor-derived transcriptomic data identifies genes with HIF1A transcription factor binding sites as enriched within brain metastases versus primary breast tumors (HIF1_Q3: P = 0.055; HIF1_Q5: P = 0.018)." (PMID 33298946, 2020). "Moreover, NCOA1 could promote angiogenesis in breast tumors by simultaneously enhancing both HIF1α- and AP-1-mediated VEGF-a transcription." (PMID 28060733, 2017). "Intratumoral hypoxia may explain elevated CA in vivo because exposure of cultured cells to hypoxia or mimicking hypoxia pharmacologically or genetically increases CA, and HIF-1α and hypoxic gene signature expression correlate with CA and centrosomal gene signature expression in breast tumors." (PMID 28272508, 2017). "The fact that aggressive IRISOE TNBC cells produce and secrete high-level IL-1β in HIF-1α and NF-κB-dependent manner is consistent with recent reports showing IL-1β is a critical mediator of inflammation leading to tumor progression within breast tumor microenvironment." (PMID 29262555, 2017). "Moreover, HIF-1α expression was found to correlate with CA in breast tumors." (PMID 28272508, 2017). "One of the roles of HIF1α is up-regulating EZH2 expression under hypoxia in breast tumor initiating cells (BTICs) that contribute to cancer progression; HIF inhibitors may potentially be effective in suppressing EZH2 oncogenic function in these cells to prevent cancer recurrence." (PMID 25115393, 2014). "Furthermore BRCA1 mutant tumours more frequently overexpress HIF1α than sporadic breast tumours." (PMID 25010005, 2014). "ZMYND8 is a transcription factor upregulated by HIF-1α and HIF-2α in human breast tumours that is correlated with poor outcomes for patients with high expression." (PMID 39282472, 2024). "This distinct role for HIF-1α and HIF-1β was demonstrated through deletion experiments conducted in mice that showed that HIF-1α and HIF-1β signaling in breast tumors control tumor dissemination in a site-specific manner." (PMID 37886168, 2023). "The levels of both HIF-1α mRNA and HIF-1α protein increased in BM-MSCs in response to breast tumor-mimicking conditions." (PMID 36230633, 2022). "To expand our findings, we assessed HIF-1α, c-Myc, and CD44 levels in our clinic breast tumor tissues." (PMID 33469161, 2021). "In the present study, LNT treatment inhibited the growth of breast tumor along with a declined VEGF and HIF-1α levels, and the decreased AKT and mTOR activities." (PMID 33245358, 2020). "In stratified tumor samples, HIF-1α expression was significantly higher in ER-positive, PR-positive, and HER2-negative breast tumors." (PMID 32707933, 2020). "We also estimated that in stratified samples, HIF-1α expression was very significantly high in ER-positive, PR-positive, and HER2-negative breast tumors compared to the control tissues." (PMID 32707933, 2020). "The increased aggressiveness of breast tumors in BNIP3-depleted mice is related to a decrease in mitophagy and the increased stability of HIF1A, indicating that BNIP3 can inhibit HIF1A and mitochondrial dysfunction." (PMID 33262988, 2020).
breast tumor (continued). "As a strong indication of up-regulated HIF signaling, we observed induction of carbonic anhydrase (CAIX), which is a gene that is dependent on HIF-1α for its expression; in addition, expression of CAIX in breast tumors correlates to poor prognosis." (PMID 29552303, 2018). "Our previous investigations have evidenced the functional cooperation between HIF-1α and GPER in the regulation of VEGF expression and angiogenesis in hypoxic breast tumor microenvironment." (PMID 29212519, 2017). "We have recently demonstrated that the G protein estrogen receptor (GPER) is a novel target gene of HIF-1α, involved in the regulation of VEGF in hypoxic breast tumor microenvironment." (PMID 29212519, 2017). "GPER is a transcriptional target of hypoxia inducible factor 1 alpha (HIF-1α) and activates VEGF expression and angiogenesis in hypoxic breast tumor microenvironment." (PMID 29212519, 2017). "Last, clinically relevant correlations between miR-18a, HIF1A, hypoxia-responsive gene expression and distant metastasis–free survival (DMFS) were assessed using published expression array breast tumors data sets." (PMID 25069832, 2014). "The positive correlation between both HIF-1α and EPAS1 (HIF-2α) mRNA levels and overall breast tumor hypoxia response suggests a role for transcriptional regulation of these hypoxia regulators." (PMID 21672245, 2011). "Moreover, hypoxia-induced angiogenic HIF1α/VEGF-A signaling was related to SDC3 upregulation in hypoxic tumors, which further implicates SDC3 in breast tumor growth and vascular remodeling." (PMID 41148827, 2025). "Further experiments are required to determine the mechanism by which BM-MSCs increase VEGF expression independent of HIF-1α in response to breast tumor cells." (PMID 36230633, 2022). "HIF-1α expression is not detected in normal breast tissue, but is present in breast tumors, supporting its potential for use as a prognostic marker for cancer recurrence." (PMID 34736510, 2021). "In situ, HIF-1α expression is significantly higher in human breast tumors (n = 96) compared to non-cancerous control tissues (n = 20) and is positively correlated with miR526b/miR655 expression." (PMID 32707933, 2020). "In order to investigate the angiocrine actions of IGF1 in breast tumour, first of all we asked whether IGF1 induces the expression of VEGF and its transcriptional regulator HIF-1α in our experimental models." (PMID 29212519, 2017). "In conclusion, in this study we identified the anti-angiogenesis role of antagomir-21 in VEGFR2-luc mouse breast tumor model via noninvasive BLI and disclosed potential mechanism of antagomir-21 in inhibiting angiogenesis via suppressing HIF-1α/VEGF/VEGFR2 signaling pathway." (PMID 23951172, 2013). "Thus, E2 stimulation of HIF-1α and consequent up regulation of VEGF leads to endothelial cell migration toward breast tumor cell secreted proteins." (PMID 23088607, 2012). "Importantly, the inhibition of ERRα significantly reduced HIF-1α activity and reversed doxorubicin efflux typical of the MDR phenotype, providing strong support for the targeting of ERRα in hypoxia-driven, chemoresistant breast tumors." (PMID 40723264, 2025). "RNA-sequencing of wild-type versus HIF-2α-deficient TAMs in murine breast tumors demonstrated 3 more genes Spint1, IL-10, and Depdc7 were downregulated by HIF-2α knockout and had an identified HIF-2α (not HIF-1α) binding site using previously published ChIP-seq data sets." (PMID 37124241, 2023). "If this is a negative feedback mechanism, it may explain why HIF-1α dominates over HIF-2α in TAM phenotype in our orthotopic murine breast tumor model." (PMID 37124241, 2023). "However, the mechanism by which ROS activates Stat3 in BM-MSCs in response to breast tumor-mimicking conditions and the mechanism by which ROS and JAK/Stat3 increase HIF-1α expression remain unclear and must be further investigated." (PMID 36230633, 2022).
breast tumor (continued). "Studies involving mice breast tumor models further elaborated that chemotherapy along with HIF inhibitors, such as digoxin (interferes with HIF1α translation) or acriflavine (inhibits dimerization of HIF1α or HIF2α with HIF1β), might improve the survival of BC patients." (PMID 35392236, 2022). "However, our results demonstrate that this activity is more common among breast tumors than the results in MCF7 would suggest, and reveal that HIF-1α inhibitors should be further explored in preclinical studies as co-therapeutics in the endocrine therapy setting." (PMID 28320353, 2017). "Our data suggest that tumors assigned to subgroup 7, which express high levels of HIF-1α and hypoxia-related genes, and subgroup 10, which express lower levels of HIF-1α and hypoxia-related genes, have characteristics in common with basal and luminal breast tumors, respectively." (PMID 21672245, 2011). "NAC treatment was therefore able to prevent the stabilization of Hif-1α and reduce VEGF secretion in response to hypoxia in both PyMT and EO771 breast tumor cells in vitro, but not alter the hypoxia-induced gene expression of VEGF and LOX." (PMID 23840457, 2013). "In addition, in contrast with our in vitro findings, we detected a negative correlation between HIF-1α and GPER gene expression in breast tumor samples." (PMID 29212519, 2017).
liver fibrosis (113 papers, 2012 to 2026). "HIF1-α is implicated in liver fibrosis, in which it augments oxidative injury; chronic HIF1-α expression was found to mediate apoptosis and liver injury." (PMID 40943413, 2025). "Over the past few decades, a large body of evidence has shown that HIF-1α is closely associated with hepatic fibrosis." (PMID 38074679, 2023). "In recent studies, HIF-1α caused liver fibrosis via PTEN/p65 signaling and interstitial fibrosis via modulation of EMT." (PMID 36714464, 2023). "Another study reported that the development mechanism of liver fibrosis is implicated in the upregulation of HIF-1α transcriptional activity and its interconnected factors, TGF-β and NF-κB, in bile duct ligation-stimulated hepatocytes fibrosis in rats." (PMID 36297027, 2022). "Ethanol along with CCL4 treatment was subjected to hepatocyte-specific HIF-1α-deficient in their study, which resulted in increased liver fibrosis induced by CCL4." (PMID 36523459, 2022). "All these gene products have been associated with the development of liver fibrosis, showing that by controlling the expression of these genes, HIF-1α can promote fibrosis." (PMID 36523459, 2022). "In earlier studies, HIF-1α was associated with TGFβ activation in hepatocytes and human umbilical vein endothelial cells during hepatic fibrosis, and TGFβ also inhibited mRNA and protein expression of PHD2, thereby increasing the stability of HIF-1α." (PMID 36119489, 2022). "The morphological imbalance and functional block of the sinusoids of the liver caused by liver fibrosis lead to liver hypoxia and induce the up-regulation of HIF1α expression." (PMID 34853322, 2021). "Studies of high cholesterol diet (HCD)-induced liver fibrosis revealed that inducible nitric oxide synthase (iNOS)-mediated enhancement of fibrosis was associated with HIF1α stabilization." (PMID 35187072, 2021). "Compared with wild-type mice, HIF1α-deficient mice have a significantly lower risk of liver fibrosis after BDL." (PMID 34853322, 2021). "HIF1A-deficient mice display reduced liver fibrosis upon injury caused by bile duct ligation (BDL), which is an established model of liver fibrosis." (PMID 31221962, 2019). "Herein, our current study showed that the increased liver fibrosis in the BDL mice was associated with an increase in bile duct epithelial CK-19 expression via up-regulation of hepatic HIF-1α level." (PMID 29156788, 2017). "Hypoxia-inducible factor-1α (HIF-1α), which functions as a key transcription factor in response to hypoxia associates with the development of hepatic fibrosis." (PMID 26863419, 2016). "Noteworthy, hypoxia-inducible factor-1α (HIF-1α) was increased in CCl4-caused liver fibrosis but abrogated by curcumin, indicating the alleviation of hepatic hypoxia state." (PMID 24779927, 2014). "The expression of HIF-1α is elevated in liver fibrosis and myocardial fibrosis caused by TGF-β1." (PMID 35682354, 2022). "HiF1α is closely related to the development of hepatic fibrosis, and liver fibrosis caused by sinus morphological imbalances and functional blocks cause hepatocytes to hypoxia, which in turn causes degradation of HIF1α to be inhibited, thereby increasing expressions." (PMID 34853322, 2021). "HIF-1α/SLC7A11 was involved in sorafenib attenuating liver fibrosis by triggering hepatic stellate cell ferroptosis." (PMID 40935814, 2025). "Immunofluorescence staining and Western blot analyses revealed that, in comparison to the control group, HIF-1α expression was significantly elevated in the liver fibrosis tissue of CCl4-induced mice." (PMID 41375167, 2025). "As such, we investigated the effects of ACBA on HIF-1α expression in CCl4-induced mouse liver fibrosis tissue." (PMID 41375167, 2025). "Accordingly, our findings reveal the protective role BCP exerts through modulating AMPK/SIRT1/HIF1-α and thus protecting against liver fibrosis." (PMID 40943413, 2025).
liver fibrosis (continued). "HIF-1α exhibits a protective effect in the liver by inhibiting hepatic lipid accumulation and a destructive effect by promoting hepatic fibrosis." (PMID 40170728, 2025). "At the 7.5 mg/kg dose, NIC significantly enhanced the expression of SIRT-1, AMPK, PGC1-α, PPARγ, and STAT3 by 2.43-, 2.56-, 3.14-, 1.76-, and 1.90-fold, respectively, compared to the TAA-induced liver fibrosis group, and reduced HIF-1α expression by 28.23%." (PMID 41365955, 2025). "Previous studies demonstrated that HIF-1α knockdown improved liver function and downregulated the expression of fibrosis-related genes in a bile duct ligation-induced hepatic fibrosis model." (PMID 41375167, 2025). "We observed that ACBA significantly reduced the expression of HIF-1α and macrophage glycolysis in liver fibrosis tissue and LPS-induced M1 macrophages." (PMID 41375167, 2025). "Studies also indicate that oxidative stress owing to excessive alcohol intake promotes HIF-1α production in hepatocytes, which induces steatosis and eventually leads to hepatic fibrosis." (PMID 40572736, 2025). "The classic Wnt/β-catenin signaling pathway promotes HSCs glycolysis by upregulating LDHA and HIF-1α, which exacerbates liver fibrosis." (PMID 40421024, 2025). "Our results have revealed that ACBA alleviates CCl4-induced hepatic fibrosis in mice by inhibiting HIF-1α-mediated macrophage polarization, but the exact binding sites and patterns between ACBA and HIF-1α need to be validated in subsequent research." (PMID 41375167, 2025). "In conclusion, these results suggest that ACBA inhibits the activity of HIF-1α, thereby decreasing macrophage glycolysis and the pro-inflammatory phenotype, which alleviates hepatic fibrosis in mice." (PMID 41375167, 2025). "In several models of renal and hepatic fibrosis and other fibrotic complications, HIF-1α signaling pathways seem to play an active role in promoting fibrosis." (PMID 39684728, 2024). "Previous studies have shown that numerous therapies targeted the HIF-1α/VEGF signaling pathway to relieve liver fibrosis." (PMID 38757304, 2024). "Mouse models of bile duct ligation and carbon tetrachloride (CCl4) combined with moderate alcohol feeding show that HIF-1α promotes liver fibrosis." (PMID 39684823, 2024). "Interleukin-8 has been found to promote carbon tetrachloride (CCl4)-induced liver fibrosis through the PI3K/Akt/HIF-1α pathway." (PMID 38961399, 2024). "Hypoxia is an important feature of hepatic fibrosis, which can upregulate the expression of HIF-1α, promote the activation of HSCs, and lead to hepatic fibrosis." (PMID 38074679, 2023). "In this study, we found that inhibiting Src activation reduced HSCs activation by decreasing HIF-1α expression, and inhibiting HSCs activation is an important way to alleviate liver fibrosis." (PMID 38077794, 2023). "During liver fibrosis, hypoxic damage occurs in liver tissue, and hypoxia-inducible factor-1α (HIF-1α) is critical in hypoxic damage, which has been confirmed by many studies." (PMID 38077794, 2023). "MiR-345-5p was recently shown to be downregulated in liver fibrosis and prevented the progression of liver fibrosis by suppressing hypoxia-inducible factor-1alpha (HIF1α) expression in mice." (PMID 37511368, 2023). "Improving the anoxic environment at the site of hepatic fibrosis and downregulating the expression of HIF-1α to the maximum extent can improve the therapeutic effect of hepatic fibrosis." (PMID 38074679, 2023). "Hypoxia is an important factor that promotes the development of liver fibrosis and the key to hypoxic damage is HIF-1α." (PMID 38077794, 2023). "In vivo experiments revealed that inhibiting Src activation in fibrotic livers reduced HIF-1α expression; meanwhile, ferroptosis was promoted, and liver fibrosis was alleviated." (PMID 38077794, 2023). "Similar to our RUP results, curcumin inhibited liver fibrosis in rats by suppressing HIF-1α/VEGF-induced angiogenesis." (PMID 36811777, 2023).